DGKZ (diacylglycerol kinase zeta)
Description:
Diacylglycerol kinase that converts diacylglycerol/DAG into phosphatidic acid/phosphatidate/PA and regulates the respective levels of these two bioactive lipids. Thereby, acts as a central switch between the signaling pathways activated by these second messengers with different cellular targets and opposite effects in numerous biological processes. Also plays an important role in the biosynthesis of complex lipids (Probable). Does not exhibit an acyl chain-dependent substrate specificity among diacylglycerol species. Can also phosphorylate 1-alkyl-2-acylglycerol in vitro but less efficiently and with a preference for alkylacylglycerols containing an arachidonoyl group. The biological processes it is involved in include T cell activation since it negatively regulates T-cell receptor signaling which is in part mediated by diacylglycerol (By similarity). By generating phosphatidic acid, stimulates PIP5KIA activity which regulates actin polymerization. Through the same mechanism could also positively regulate insulin-induced translocation of SLC2A4 to the cell membrane (By similarity). [Isoform 1]: Regulates RASGRP1 activity. [Isoform 2]: Does not regulate RASGRP1 activity.
Synonyms: DGK-zeta; DAGK6; DAGK5; hDGKzeta
Tractability: Antibody: UniProt places it where antibodies can reach, with high confidence; its Gene Ontology location is reachable by antibodies, with high confidence. PROTAC: ubiquitination databases record sites on it; its protein half-life has been measured; a small molecule that binds it is known.
Target class: Enzyme; Transferase
Gene: Protein-coding gene on chromosome 11 (46,332,905 to 46,380,554, forward strand). Ensembl gene ENSG00000149091.
Subcellular location: Nucleus; Cytoplasm, cytosol; Cell membrane; Cell projection, lamellipodium
Subcellular location (Human Protein Atlas): Nuclear speckles
Pathways (Reactome):
Hemostasis: Effects of PIP2 hydrolysis
Gene Ontology:
Molecular function: ATP-dependent diacylglycerol kinase activity; kinase activity; protein binding; ATP binding; alkylglycerol kinase activity
Biological process: diacylglycerol metabolic process; glycerolipid metabolic process; lipid phosphorylation; phosphatidic acid biosynthetic process; cell migration; intracellular signal transduction; negative regulation of T cell receptor signaling pathway; platelet activation; phospholipase C-activating G protein-coupled receptor signaling pathway; signal transduction
Cellular component: cytosol; lamellipodium; nuclear speck; nucleus; plasma membrane; cytoplasm; glutamatergic synapse
Genetic constraint (gnomAD): Loss-of-function variants: 45 observed, 128.04 expected, observed/expected ratio (o/e) 0.35, 90% interval 0.28 to 0.45. The upper end of that interval is the gene's LOEUF score, 0.45, which puts it in group 2 of 6, group 1 being the genes least tolerant of losing a copy. Missense variants: 755 observed, 1,134.5 expected, observed/expected ratio (o/e) 0.67, 90% interval 0.63 to 0.71. Synonymous variants: 442 observed, 450.61 expected, observed/expected ratio (o/e) 0.98, 90% interval 0.91 to 1.06.
Homologues: Orthologues: chimpanzee DGKZ (97% identical), macaque DGKZ (96% identical), dog DGKZ (94% identical), pig DGKZ (94% identical), guinea pig DGKZ (94% identical), rat Dgkz (93% identical), mouse Dgkz (92% identical), zebrafish dgkza (74% identical), tropical clawed frog dgkz (73% identical), zebrafish dgkzb (63% identical), Drosophila melanogaster rdgA (40% identical), Caenorhabditis elegans dgk-5 (35% identical), and 2 more. Paralogues in human: DGKI (63% identical), DGKD (25% identical), DGKH (24% identical), DGKG (22% identical), DGKK (21% identical), DGKB (21% identical), DGKA (20% identical), DGKQ (19% identical), DGKE (18% identical).
Diseases named in the same sentence as DGKZ in open-access papers:
DGKZ is named in the same sentence as 35 diseases in open-access papers, as found by Europe PMC text mining. Sharing a sentence is not in itself a finding about the gene and the disease. The quoted sentences say what the papers report.
colon carcinoma (3 papers, 2018 to 2022). "DGKZ also promotes Rho GTPase activity and contributes to enhanced invasion in metastatic colon cancer cells." (PMID 36232920, 2022). "For example, DGKZ controls mRORC1 function to affect the colon cancer survival." (PMID 33926342, 2021). "Recent studies have proven that in colon cancer and gliomas, DGKZ plays an key role in oncogenesis." (PMID 30662872, 2018).
glioma (3 papers, 2018 to 2022). A benign or malignant brain and spinal cord tumor that arises from glial cells (astrocytes, oligodendrocytes, ependymal cells). "Downregulation of DGKZ inhibits the cell proliferation and survival in human gliomas." (PMID 33926342, 2021). "Furthermore, DGKZ knockdown in human glioma suppressed cell proliferation, hampered colony formation ability, and promoted cell cycle arrest and apoptosis." (PMID 30662872, 2018). "In addition, several studies have revealed that DGKZ functions as a promotor in human glioma, colorectal cancer, and cervical cancer, but its role in breast cancer remains unclear." (PMID 35115500, 2022).
osteosarcoma (3 papers, 2018 to 2022). A usually aggressive malignant bone-forming mesenchymal neoplasm, predominantly affecting adolescents and young adults. "In our study, through IP-MS analysis, we provided potential evidence that the interaction of ERK1/2 and DGKZ was closely linked to MYC-dependent osteosarcoma development." (PMID 30662872, 2018). "DGKZ expression was associated with a poor prognosis in IIB limb osteosarcoma patients." (PMID 30662872, 2018). "DGKZ is reported to act as an oncogene in osteosarcoma (OS) and is correlated with poor prognoses of OS patients, but the relationship between DGKZ and PDAC is lacking." (PMID 34930261, 2021). "To initially detect expression of DGKZ in osteosarcoma, we collected 80 osteosarcoma samples and 24 normal bone samples." (PMID 30662872, 2018). "Taken together, these data indicated substantial evidence that DGKZ is a prognostic marker and potential new target for cancer therapy in osteosarcoma." (PMID 30662872, 2018). "Among 80 tumor samples, 37 osteosarcoma samples(46.2%) had high expression of DGKZ with a score defined as positive (above 6)." (PMID 30662872, 2018). "To investigate the potential mechanism about DGKZ in regulating tumorigenesis of osteosarcoma, we conducted microarray analysis to explore alteration of cancer-related genes between normal osteosarcoma cells and DGKZ knockdown cells." (PMID 30662872, 2018). "Consistent with findings in vitro, our data also strongly supported the positive correlation between DGKZ expression and osteosarcoma growth." (PMID 30662872, 2018). "In our study, DGKZ's expression was upregulated in osteosarcoma tissues and correlated with patients' poor prognosis." (PMID 30662872, 2018). "In conclusion, our study demonstrated that DGKZ, a potential prognostic and predictive indicator in osteosarcoma, play a key role in proliferation of osteosarcoma, via its possible interaction with ERK1/2 and regulation of MYC pathway." (PMID 30662872, 2018). "In bones, DGKZ is thought to have an oncogenic effect by promoting osteosarcoma and may play a key role in osteoclast differentiation." (PMID 35769265, 2022). "In summary, these results demonstrated that OS patients with high DGKZ expression survived for shorter periods than those with low DGKZ expression and DGKZ might played an essential role in the development and progression of osteosarcoma." (PMID 30662872, 2018). "The previous data suggested that DGKZ played a key role in osteosarcoma growth." (PMID 30662872, 2018). "Taken together, it could be concluded that DGKZ might exert an enhancing effect on activity of MYC signal pathway to impact on osteosarcoma proliferation." (PMID 30662872, 2018). "In vitro, DGKZ knockdown impaired proliferation and promoted apoptosis in osteosarcoma cells." (PMID 30662872, 2018). "Together, our study demonstrated that DGKZ might act as an oncogene in osteosarcoma via its possible interaction with ERK1/2 and MYC pathway." (PMID 30662872, 2018). "Silence of DGKZ by shRNA hampered osteosarcoma cell growth and promoted cell apoptosis in vitro." (PMID 30662872, 2018). "Taken together, these data imply that role of DGKZ in osteosarcoma pathogenesis may function via regulation of MYC signal pathway." (PMID 30662872, 2018). "However, the role of DGKZ in proliferation of osteosarcoma is still unclear." (PMID 30662872, 2018). "Additionally, DGKZ also showed its function in regulating bone homeostasis through osteoclasts via modulation of c-Fos, which is a key regulator in proliferation of osteosarcoma." (PMID 30662872, 2018). "We next examined whether DGKZ silencing in osteosarcoma affects OS cell growth in vivo." (PMID 30662872, 2018). "In our study, we speculated that DGKZ acts as an oncogene in proliferation of osteosarcoma." (PMID 30662872, 2018). "However, the potential role of DGKZ in oncogenesis of osteosarcoma is still unclear." (PMID 30662872, 2018).
osteosarcoma (continued). "Of note, osteosarcoma develops in some cases of advanced stages of PDB and our data showed decreased methylation in the promotor region of DGKZ with increased disease severity." (PMID 35769265, 2022). "Compared with osteosarcoma samples, DGKZ expression was absent in normal bone samples while all bone samples demonstrated a score defined as negative(≤6)." (PMID 30662872, 2018). "Additionally, microarray and IPA analyses demonstrated a alternation in expression of signaling-related genes in osteosarcoma cells and verified MYC pathway as a direct downstream target of DGKZ." (PMID 30662872, 2018). "Whether regulation of DGKZ on downstream MYC pathway in osteosarcoma is through a direct or indirect route is still not clear." (PMID 30662872, 2018).
schizophrenia (3 papers, 2021 to 2025). A major psychotic disorder characterized by abnormalities in the perception or expression of reality. "The schizophrenia susceptibility genes detected in inh-PVALB neurons in the midbrain included genes such as DGKZ, INPP4B and TKT." (PMID 39397771, 2025). "One of the examples is DGKZ, the functional relevance of which to schizophrenia (SCZ) has been implicated in previous work." (PMID 35982161, 2022). "DGKZ is located within a schizophrenia GWAS loci and is further known to be dysregulated in schizophrenia patients." (PMID 33892787, 2021).
triple-negative breast carcinoma (3 papers, 2022 to 2024). An invasive breast carcinoma which is negative for expression of estrogen receptor (ER), progesterone receptor (PR), and human epidermal growth factor receptor 2 (HER2). "Diacylglycerol kinase zeta (DGKZ) was shown to promote TGF-β signaling in triple-negative breast cancer." (PMID 36232920, 2022). "Next, knockout of DGKZ in triple-negative breast cancer cell lines were found to significantly inhibit metastatic behaviors in vitro and in vivo, whereas its overexpression increased the metastatic potential of cell lines." (PMID 35115500, 2022). "Overexpression of DGKZ significantly reduced the expression of E-cadherin, while increasing the expression of N-cadherin and FN-1, and the cytoskeletal morphology of the cells had significant changes, indicating that DGKZ participated in the induction of EMT in triple-negative breast cancer cells." (PMID 35115500, 2022).
cervical cancer (2 papers, 2021 to 2022). A primary or metastatic malignant neoplasm involving the cervix. "In summary, downregulation of DGKZ impeded cell proliferation, boosted cell apoptosis and induced cell cycle arrest to suppress tumorigenesis and progression of cervical cancer." (PMID 33926342, 2021). "DGKZ expression in cervical cancer tissues and paired adjacent normal cervical tissues was assessed using Immunohistochemistry assay." (PMID 33926342, 2021). "Here, the current work aims to identify the functional role of DGKZ in cervical cancer (CC)." (PMID 33926342, 2021). "A recent study showed that differentially expressed proteins induced by silencing of DGKZ in cervical cancer were mostly enriched in autophagy or mitophagy, indicating that the functions of DGKZ in cell proliferation and tumor growth may be associated with autophagy or mitophagy." (PMID 35115500, 2022).
Obesity (2 papers, 2013 to 2025). Accumulation of substantial excess body fat. "DGKZ has been implicated as a member of the downstream leptin signaling pathway and reduced expression or activity within the hypothalamus has been associated with obesity." (PMID 23758707, 2013).
acute monocytic leukemia (1 paper, 2023). Acute monoblastic leukemia (AML-M5), is one of the most common subtypes of acute myeloid leukemia (AML) that is either comprised of more than 80% of monoblasts (AML-M5a) or 30-80% monoblasts with (pro)monocytic differentiation (AML-M5b). "DGKH consistently showed the lowest expression except in acute monocytic leukemia (AMOL), while DGKZ, DGKD, DGKQ and DGKA exhibited the highest expression levels." (PMID 37509516, 2023).
Alzheimer disease (1 paper, 2014). A progressive, neurodegenerative disease characterized by loss of function and death of nerve cells in several areas of the brain leading to loss of cognitive function such as memory and language. "The DGKZ gene encodes diacylglycerol (DAG) kinase zeta, a member of the DAG kinase family which phosphorylates DAG to phosphatidic acid and plays important roles in lipid signaling implicated in neurological diseases, including epilepsy, depression and Alzheimer's disease." (PMID 24831815, 2014).
autoimmune myocarditis (1 paper, 2023). Autoimmune myocarditis is an autoimmune disease that affects the heart. "Based on protein structure, function, and subcellular organelle regulation, we also found that DGKZ protein may be an important regulatory gene of tumor-related autoimmune myocarditis and can be a potential therapeutic target." (PMID 37388276, 2023).
breast carcinoma (1 paper, 2022). "Additionally, multivariate analysis revealed that high expression of DGKZ was an independent risk factor for breast cancer recurrence and metastasis." (PMID 35115500, 2022). "Moreover, high DGKZ expression is closely associated with lung metastasis in mouse breast cancer models." (PMID 35115500, 2022). "TMAs of samples from breast cancer patients revealed that high DGKZ expression correlated with poor prognosis." (PMID 35115500, 2022). "By using Oncomine expression analysis, we recognized that DGKZ underwent a copy number elevation in tissues of invasive breast cancer, suggesting that the potential importance of DGKZ in oncogenesis and progression of breast cancer." (PMID 35115500, 2022). "Our results suggest that further studies should be established to find the potential clinical utility of DGKZ as a prognostic biomarker for aggressive breast carcinoma." (PMID 35115500, 2022). "Diacylglycerol kinase ζ (DGKZ) is a diacylglycerol kinase that metabolizes diacylglycerol to yield phosphatidic acid, and its function in breast cancer progression remains unclear." (PMID 35115500, 2022). "DGKZ was highly expressed in 93 cases of breast cancer and expressed at low levels in 103 cases." (PMID 35115500, 2022). "In addition, analyses of the Oncomine database and Human Cancer Metastasis Database (HCMDB) revealed that DGKZ was upregulated in breast carcinoma compared with normal breast tissues." (PMID 35115500, 2022).
breast tumors (1 paper, 2022). "On the basis of data from the HCMDB, the expression level of DGKZ is much higher in primary breast tumors or primary tumors with metastasis than in normal breast tissue or primary tumors without metastasis." (PMID 35115500, 2022).
chondrosarcoma (1 paper, 2015). A malignant cartilaginous matrix-producing mesenchymal neoplasm arising from the bone and soft tissue. "For each cancer type, we found at least one new potential cancer-associated domain instance, for example, the diacylglycerol kinase domain encoded by DGKZ in chondrosarcoma." (PMID 25794154, 2015).
colorectal tumors (1 paper, 2022). "Furthermore, DGKZ activation downstream of mTORC2 in rapamycin-resistant colorectal tumors helps to maintain the DAG/PA balance necessary for cell survival, and DGKZ suppression potentiates the growth-inhibitory effect of rapamycin." (PMID 35115500, 2022).
coronary artery diseases (1 paper, 2023). "It is reported that DGKZ involved in the phosphatidylinositol signal pathway is closely related to pathway mechanisms in coronary artery diseases." (PMID 37388276, 2023).
endothelial dysfunction (1 paper, 2025). In vascular diseases, endothelial dysfunction is a systemic pathological state of the endothelium (the inner lining of blood vessels) and can be broadly defined as an imbalance between vasodilating and vasoconstricting substances produced by (or acting on) the endothelium. "AChE and DGKZ directly modulate smooth muscle function, while NLRP3 inflammasome contributes to endothelial dysfunction and smooth muscle cell pyroptosis, and PLD2 is involved in angiotensin generation." (PMID 39981435, 2025).
epilepsy (1 paper, 2014). A brain disorder characterized by episodes of abnormally increased neuronal discharge resulting in transient episodes of sensory or motor neurological dysfunction, or psychic dysfunction. "Moreover, mice deficient in the gene encoding DAG kinase, epsilon (Dgke) a member of the same gene family, exhibit features associated with epilepsy, suggesting the DGKZ substitution mutation may contribute to the pathogenesis of the patient's seizures." (PMID 24831815, 2014).
Huntington disease (1 paper, 2022). Huntington disease (HD) is a rare neurodegenerative disorder of the central nervous system characterized by unwanted choreatic movements, behavioral and psychiatric disturbances and dementia. "Four of these were differently expressed in Huntington’s disease compared with WT in SH: IP3KA, KPCB, KPCA and DGKZ." (PMID 36523271, 2022).
myocarditis (1 paper, 2023). Myocarditis is a condition that is characterized by inflammation of the heart muscle (myocardium). "Mitochondrial-regulated glycerolipid metabolism, especially the DGKZ protein, plays a key role in the metabolic reprogramming of immunotherapy-related myocarditis." (PMID 37388276, 2023).
osteopetrosis (1 paper, 2024). Osteopetrosis, also known as marble bone disease, is a descriptive term that refers to a group of rare, heritable disorders of the skeleton characterized by increased bone density on radiographs. "Therefore, we speculate that DGKQ and DGKZ may be involved in the pathogenesis of osteopetrosis by regulating the level of DAG." (PMID 40018371, 2024).
pheochromocytoma (1 paper, 2019). "Similarly, mutations only associated with pheochromocytoma severely affect the DGKZ, PRKCI, PRKCD and PRKCZ kinase binding interfaces, further suggesting a link between hypoxia sensing and phosphorylation-mediated signaling." (PMID 30943211, 2019).